IGLV1-44 (immunoglobulin lambda variable 1-44)
Description:
V region of the variable domain of immunoglobulin light chains that participates in the antigen recognition. Immunoglobulins, also known as antibodies, are membrane-bound or secreted glycoproteins produced by B lymphocytes. In the recognition phase of humoral immunity, the membrane-bound immunoglobulins serve as receptors which, upon binding of a specific antigen, trigger the clonal expansion and differentiation of B lymphocytes into immunoglobulins-secreting plasma cells. Secreted immunoglobulins mediate the effector phase of humoral immunity, which results in the elimination of bound antigens. The antigen binding site is formed by the variable domain of one heavy chain, together with that of its associated light chain. Thus, each immunoglobulin has two antigen binding sites with remarkable affinity for a particular antigen. The variable domains are assembled by a process called V-(D)-J rearrangement and can then be subjected to somatic hypermutations which, after exposure to antigen and selection, allow affinity maturation for a particular antigen.
Synonyms: IGLV144; V1-16
Tractability: Antibody: its Gene Ontology location is reachable by antibodies, with high confidence; UniProt places it where antibodies can reach, with medium confidence; UniProt predicts a signal peptide or a membrane-spanning region.
Gene: Immunoglobulin variable (V) gene on chromosome 22 (22,380,766 to 22,381,347, forward strand). Ensembl gene ENSG00000211651.
Subcellular location: Secreted; Cell membrane
Pathways (Reactome):
Immune System: Antigen activates B Cell Receptor (BCR) leading to generation of second messengers; CD22 mediated BCR regulation; Classical antibody-mediated complement activation; FCERI mediated Ca+2 mobilization; FCERI mediated MAPK activation; FCERI mediated NF-kB activation; FCGR activation; Fc epsilon receptor (FCERI) signaling; Immunoregulatory interactions between a Lymphoid and a non-Lymphoid cell; Initial triggering of complement; Regulation of Complement cascade; Regulation of actin dynamics for phagocytic cup formation; Role of LAT2/NTAL/LAB on calcium mobilization; Role of phospholipids in phagocytosis
Disease: FCGR3A-mediated IL10 synthesis; FCGR3A-mediated phagocytosis; Potential therapeutics for SARS
Hemostasis: Cell surface interactions at the vascular wall
Vesicle-mediated transport: Scavenging of heme from plasma
Gene Ontology:
Molecular function: antigen binding
Biological process: immune response
Cellular component: extracellular region; immunoglobulin complex; plasma membrane
Homologues: Paralogues in human: IGLV1-47 (96% identical), IGLV1-36 (85% identical), IGLV1-40 (81% identical), IGLV1-51 (79% identical), IGLV1-50 (77% identical), IGLV2-18 (70% identical), IGLV2-8 (68% identical), IGLV2-11 (66% identical), IGLV6-57 (66% identical), IGLV2-14 (65% identical), IGLV2-23 (65% identical), IGLV2-33 (60% identical), and 81 more.
Diseases named in the same sentence as IGLV1-44 in open-access papers:
IGLV1-44 is named in the same sentence as 1 disease in open-access papers, as found by Europe PMC text mining. Sharing a sentence is not in itself a finding about the gene and the disease.
IGLV1-44 shares sentences with these, for which no sentence is quoted: colorectal cancer (1 paper).